IGF1R (insulin like growth factor 1 receptor)
Diseases named in the same sentence as IGF1R in open-access papers (continued):
Sharing a sentence is not in itself a finding about the gene and the disease.
glioma (97 papers, 2009 to 2026). A benign or malignant brain and spinal cord tumor that arises from glial cells (astrocytes, oligodendrocytes, ependymal cells). "Exogenous IGF-1 can enhance the invasive and migratory capacity of glioma cells by binding to IGF-1R and has been associated with resistance of gliomas to radiation, chemotherapy, and immunotherapy." (PMID 40243478, 2025). "IGF-1R is a multifunctional membrane-associated tyrosine kinase, which potentially facilitates the glioma patient’s response to kinase-inhibiting drugs such as WZ.1.184, BMS.509744, and A770041." (PMID 38665430, 2024). "IGF1R inhibitors have recently gained traction in clinical trials for diverse malignancies, and their potential role in glioma, especially high-risk subsets, opens avenues for targeted therapeutic strategies." (PMID 39434883, 2024). "Considering the significant role played by IGF-1R signaling in carcinogenesis pathways as well as the poor prognosis associated with glioma, further investigation of the IGF-1R-related signaling pathway genes in glioma is necessary." (PMID 38665430, 2024). "In this study, we used the IGF-1R-related signaling pathway genes to develop a predictive risk model for further investigation of their role in glioma." (PMID 38665430, 2024). "Previously, we have demonstrated that, in pediatric gliomas, IGF1R nuclear localization is significantly associated with high-grade tumors, worst clinical outcome, and increased risk of death." (PMID 35574033, 2022). "In a previous study conducted by our group in which tumor samples from pediatric gliomas were analyzed, we have demonstrated that IGF1R nuclear localization is associated with higher-grade tumors and also related with worst clinical outcome of those patients." (PMID 35574033, 2022). "A similar result was obtained using a different IGF1R inhibitor, genetic knockout of endogenous IGF1R, in multiple mouse and human primary glioma cell lines with different genetic mutations." (PMID 33173731, 2020). "Using genetic mouse models with NSCs or OPCs as the glioma cells‐of‐origin/mutation, it is shown that desirable outcomes of IGF1R knockout on cell growth require mutant cells with the development hierarchy to commit to the OPC identity." (PMID 33173731, 2020). "In this study, we report that the susceptibility of glioma cells to IGF1R targeting is determined not only by its oncogenic state, but also by its cell identity/state within the hierarchy of tumor development." (PMID 33173731, 2020). "We examined the mechanisms underlying the loss of IGF-1R-inhibited cellular growth and metabolism through the Akt pathway in glioma cells." (PMID 25394492, 2014). "Additionally, the expression levels of HRAS, MAPK1, IGF1, and IGF1R in glioma cells have been closely linked to the growth, invasion, and metastasis of glioma." (PMID 37865727, 2023). "Additionally, IGF1R knockdown inhibited anchorage-independent growth of glioma cells, associated with a decreased glycolytic phenotype." (PMID 28969033, 2017). "In gliomas, miR-383 targets insulin-like growth factor 1 receptor (IGF1R), leading to suppression of AKT signaling and downregulation of matrix metalloproteinase 2 (MMP2), thereby inhibiting glioma cell invasion." (PMID 38625593, 2025). "The signaling pathways through which IGF1R, activated by HIF1α and HIF2α, promotes tumor cell proliferation and therapy resistance in glioma cells are also worth exploring." (PMID 40290443, 2025). "Beyond the BBB, IGF-1R is also expressed in glioma cells and brain metastases, where it contributes to tumor proliferation, survival, and therapeutic resistance." (PMID 40806198, 2025). "For example, NCK1-AS1 overexpression increases IGF1R expression, further promoting glioma cell proliferation and resistance to radiotherapy and chemotherapy." (PMID 40290443, 2025). "We analyzed the expression and correlation of HIF1α, HIF2α, and IGF1R in glioma using The Cancer Genome Atlas (TCGA) and Chinese Glioma Genome Atlas (CGGA) databases." (PMID 40290443, 2025).
glioma (continued). "Accordingly, we conducted research and found that TCGA and CGGA databases indicate a positive correlation between HIF1α, HIF2α, and IGF1R expression in glioma tissues." (PMID 40290443, 2025). "This study provides the basis for further exploration of enhanced personalized treatment options for patients with glioma using IGF-1R-related pathway genes." (PMID 38665430, 2024). "In the present study, we analyzed the response of patient-derived pediatric high-grade glioma cells to a novel IGF-1R inhibitor, the IGF-Trap." (PMID 37259440, 2023). "BMS-754807 is also an IGF-1R inhibitor reported to prevent radiotherapy resistance in pediatric/youth high-grade gliomas." (PMID 36845382, 2023). "With this work, we provide evidence supporting the implications of the presence of IGF1R in the nucleus of glioma cells and a potential therapeutic opportunity for patients harboring gliomas with IGF1R nuclear localization." (PMID 35574033, 2022). "In a previous study, we analyzed the mRNA expression of IGF1R in pediatric low- and high-grade gliomas." (PMID 35574033, 2022). "The present study was designed to explore the role of IGF1R intracellular localization in the biology of pediatric high-grade glioma in vitro and, using subcutaneous xenografts as a proof of concept, by in vivo studies." (PMID 35574033, 2022). "Considering these data, we selected U87WT and U87Mut clones as the ones which better represented high-grade gliomas, regarding the mRNA expression of IGF1R." (PMID 35574033, 2022). "Recently published work has shown that in vitro radiation selection of human and mouse-derived glioma stem cells can induce the insulin like growth factor 1 receptor–mediated (IGF1R-mediated) resistance pathway via N-cadherin upregulation." (PMID 35852875, 2022). "Though we are aware of the limitations of the model, we considered that the chosen clones better represented the pediatric gliomas regarding mRNA IGF1R expression levels." (PMID 35574033, 2022). "The present study was designed to explore the effects of IGF1R nuclear localization previously observed in pediatric high-grade gliomas." (PMID 35574033, 2022). "In conclusion, miR-378a-3p can directly inhibit the growth of glioma cells and promote apoptosis by targeting IGF1R expression, thereby enhancing the sensitivity to CDDP." (PMID 34761108, 2021). "In this study, we investigated the molecular mechanism by which miR-378a-3p regulates cisplatin (CDDP) chemosensitivity in glioma cells via insulin-like growth factor 1 receptor (IGF1R)." (PMID 34761108, 2021). "The IGF-1R is involved in various human cancers, such as ovarian, breast, pancreatic, glioma, hepatocellular, lymphoma, and non-small lung cancers." (PMID 33768092, 2021). "This study confirmed that miR-378a-3p promoted the sensitivity of glioma cells to CDDP in glioma patients via targeting IGF1R to increase the therapeutic effect during chemotherapy." (PMID 34761108, 2021). "The findings herein identify the cellular window of IGF1R targeting, and firmly establish IGF1R as an effective target for glioma prevention and treatment." (PMID 33173731, 2020). "In contrast, the glioma incidence significantly decreased in the CKO_NG2‐CreER_IGF1R (flox/flox) mice, indicating that IGF1R deactivation restrained OPC transformation." (PMID 33173731, 2020). "Given the poor ability of currently available IGF1R inhibitors to penetrate the brain, clinical trials of IGF1R targeting in gliomas lag behind those focusing on other solid tumors." (PMID 33173731, 2020). "In the mouse glioma cell line, IGF1R highly overlapped not only with the OPC marker PDGFRα, but also with those marking proliferation and stemness." (PMID 33173731, 2020). "Promising results were also obtained with a treatment based on autologous glioma cells treated ex vivo with an antisense oligodeoxynucleotide targeting the IGF-IR (IGF-1R/AS ODN) and re-implanted in patients." (PMID 33604294, 2020).
glioma (continued). "Among the selected genes, 15 (Araf, Braf, Kras, Ccnd1, Cdk6, Igf1r, Nras, Pik3ca, Pik3r1, Pdgfra, Pdgfrb, Pdgfb, Akt1, Akt2, and Mdm2) were related to glioma and leukemia." (PMID 31523185, 2019). "LINC01023 is a regulator of the IGF1R/Akt pathway in glioma, again a signaling pathway that has been shown to regulate CF lung disease." (PMID 31842871, 2019). "Taken together, these results indicate that IGFBP6 produced by TMZ-sensitive glioma cells can modulate IGF-1R/AKT signaling in TMZ-resistant cells." (PMID 30231881, 2018). "IGF-1R was significantly upregulated in astrocytoma, oligodendroglioma, and mixed glioma, whereas IGF-1R expression in glioma samples overall was lower and comparable to that in non-tumor tissues." (PMID 30231881, 2018). "While most studies in glioma have characterized individual components of the IGF/IGF-1R axis, our results show that intratumoral interactions between TMZ-resistant and TMZ-sensitive cells involve the IGF system and drive the fate of the tumor." (PMID 30231881, 2018). "Our observations suggest that IGF-1R/IGF2 can be considered a potential target for the treatment of chemoresistant gliomas." (PMID 30231881, 2018). "Our results demonstrated that overexpression of miR‐497 is significantly correlated with TMZ resistance in glioma cells by regulating the IGF1R/IRS1 pathway." (PMID 28064447, 2017). "For glioma, inhibition of IGF-1R is shown to enhance the sensitivity to etoposide, which also targets topoisomerase." (PMID 26274927, 2015). "In the present study, GSK1904529A, a small molecule inhibitor of IGF-1R, suppressed glioma cell viability, induced glioma cell apoptosis and inhibited glioma cell migration in vitro." (PMID 26035416, 2015). "In conclusion, the present study suggested the importance of the IGF/IGF-1R signaling pathway for the treatment of glioma." (PMID 26035416, 2015). "Previous studies have reported that miR-181b-5p functions in gliomas to suppress growth by targeting the IGF-1R oncogene and modulates glioma cell sensitivity to temozolomide by targeting MEK1." (PMID 25299073, 2014). "Forced expression of miR-7 or IGF-1R knockdown inhibited colony formation and glucose metabolic capabilities of glioma cells in vitro and decreased the p-Akt expression level." (PMID 25394492, 2014). "Cell invasion promoted by miR-383 inhibition was rescued by IGF-1R inhibition suggesting that miR-383 functions as tumor suppressor by targeting IGF-1R directly and regulating IGF-1R-mediated cell invasion in glioma." (PMID 25628647, 2014). "Recently, miR-181b-5p was found to inhibit glioma cell proliferation, migration, invasion and tumorigenesis by targeting IGF-1R and to reduce chemoresistance to temozolomide in glioma cells by targeting MEK1." (PMID 25299073, 2014). "This study provides the first evidence that miR-7 inhibits cellular growth and glucose metabolism in gliomas, at least partially, by regulating the IGF-1R/Akt signaling pathway." (PMID 25394492, 2014). "Taken together, the results of the present study demonstrated that miR-503 is a tumor suppressor for GBM and a favorable factor against glioma progression through targeting IGF-1R, thus providing a new evidence-supported prognostic marker for GBM diagnosis." (PMID 24378652, 2014). "In an earlier paper we identified the insulin growth factor receptor type I gene (IGF1R) as important in the development of glioblastoma, and therefore we concentrated on the Glioma-pathway which is highly depended on IGF1R as an example." (PMID 19785734, 2009). "IGF-1R is widely present and highly expressed in glioma cells." (PMID 40243478, 2025). "In summary, under hypoxia, HIF1α and HIF2α regulate downstream IGF1R expression in glioma cells." (PMID 40290443, 2025).
glioma (continued). "One specific study (NCT01550523) assessed glioma cell–derived exosomes that were engineered to carry an antisense molecule against the insulin-like growth factor I receptor (IGF1R), demonstrating both the feasibility and safety of exosome-based therapeutic delivery." (PMID 41142789, 2025). "However, the relationship between the IGF-1R-related signaling pathway genes and glioma prognosis or immunotherapy/chemotherapy is poorly understood." (PMID 38665430, 2024). "Therefore, in this study, we initially identified IGF-1R-related signaling pathway genes with prognostic value in patients with glioma by analyzing multiple public cohorts and their corresponding survival information." (PMID 38665430, 2024). "Previous studies have shown that BMS-754807, as an inhibitor of IGF1R/IR, may be used in the treatment of gliomas and SKCM." (PMID 38691253, 2024). "Insulin-like growth factor 1-receptor (IGF-1R) gene amplifications have been identified in high-grade gliomas and may contribute to its highly aggressive phenotype, but the effect of IGF inhibitors on pHGG is yet to be determined." (PMID 37259440, 2023). "Glioma may acquire resistance driven by elevating levels of high IGF-1R and macrophage-derived IGF-1, which enhance survival and invasion of glioma cells." (PMID 37012233, 2023). "NVP-AEW541 + Dasatinib through dual IGF1R and Src inhibition increases apoptosis in glioma cells." (PMID 38002561, 2023). "Higher IGF1R expression is associated also with shorter overall survival in paediatric but not adult glioma." (PMID 34554347, 2022). "Interestingly, the link between CPD and IGF1R is largely abrogated in glioma cells, while the CPD-FURIN relationship is maintained." (PMID 35768873, 2022). "Furthermore, mouse glioma stem cells induced by radiation at intervals induce radiation resistance by upregulating IGF-1R expression." (PMID 36555406, 2022). "We have found that IGF2R, INSR, and IGF1R have a tight relationship with SOX10 in gliomas." (PMID 36524115, 2022). "MiR-323-5p can reportedly act as a tumour suppressor in human glioma cells by targeting the insulin-like growth factor 1 receptor, can inhibit cell proliferation by blocking IGF-1R-mediated migration; however; its role in ageing-related angiogenesis has not been reported." (PMID 35366240, 2022). "WT 5 (U87WT 5) and Mut 5 (U87Mut 5) cells had comparable levels of IGF1R mRNA expression than those observed in samples from high-grade gliomas from pediatric patients (P GB) that we used as a reference for expression levels, while U87WT50 and U87Mut 50 expressed much higher mRNA levels of IGF1R." (PMID 35574033, 2022). "Taken together, data indicate that intracellular IGF1R distribution may help in stratifying pediatric glioma patients." (PMID 36479090, 2022). "Knockdown of linc01023 by regulating the IGF-1R/AKT axis could restrain glioma proliferation, migration, and invasion." (PMID 33768092, 2021). "Therefore, the aim of the present study was to validate the involvement of IGF1R in the regulatory effects of miR-378a-3p on CDDP chemosensitivity in glioma cells." (PMID 34761108, 2021). "Therefore, we conclude that in human gliomas, particularly GBMs, IGF1R‐mediated signaling can be activated in tumor OPCs that are undergoing proliferation." (PMID 33173731, 2020). "In fact, our scRNA‐seq data revealed that endothelial cells in glioma strongly expressed IGF1R, which could be the target of IGF1R antagonists." (PMID 33173731, 2020). "To further determine the role of IGF1R in the growth of human OPC tumor cells in vivo, we acutely transfected patient‐derived glioma cells with Piggybac (PB) transposon vectors encoding multiplex miRNAs against different sites of IGF1R (Mir‐IGF1R) or against Luciferase (Mir‐Luc)." (PMID 33173731, 2020). "Finally, elevated expression of IGF-1R and IGF2 in gliomas associated with poor patient survival and tumor expression levels of IGFBP6 directly correlated with overall survival time in patients with GBM." (PMID 30231881, 2018).
glioma (continued). "Indeed miR-181b in-vitro overexpression reduced IGF-1R expression levels; in glioma clinical specimens, an inverse correlation between miR-181b and IGF-1R has been observed thus confirming the in-vitro results." (PMID 30469501, 2018). "We hypothesized that miR‐497 could regulate TMZ resistance in glioma cells by targeting IGF1R/IRS1 pathway." (PMID 28064447, 2017). "In conclusion, our results are consistent with the hypothesis that miR‐497 as a glioma promoter, is significantly correlated with the TMZ resistance of human glioma cells by targeting the IGF1R/IRS1 pathway both in vitro and in vivo." (PMID 28064447, 2017). "Interestingly, the treatment of tumours formed by this radioresistant glioma stem cells with picropodophyllin (an IGF1R inhibitor) increased the radiosensitivity." (PMID 28880250, 2017). "Our results demonstrated that the down‐regulation of miR‐497 could inhibit the levels of IGF1R/IRS1 signal pathway‐related proteins in TMZ‐resistant glioma cells both in vitro and in vivo." (PMID 28064447, 2017). "We demonstrated that miR‐497 could regulate TMZ resistance in glioma cells by promoting cell proliferation and inhibiting apoptosis, at least partially, via targeting the IGF1R/IRS1 pathway." (PMID 28064447, 2017). "Moreover, recent studies demonstrated that a number of cell cycle-related and invasion-associated genes are regulated by IGF-1R, including CCND1 and MMP-2/MMP-9 in human glioma and head and neck cancer, which function through MAPK and PI3K/AKT pathways." (PMID 24378652, 2014). "The progression of glioma is correlated with increased expression level of IGF-1R." (PMID 24378652, 2014). "Furthermore, the microglia could be the target cell with elevated IGF‐1/IGF‐1R signaling in the glioma treatment." (PMID 37849438, 2023). "Finally, immunohistochemical analyses identified IGF1R staining in 47 out of 53 pediatric gliomas." (PMID 36479090, 2022). "However, the specific effect of IGF1R on glioma is still unclear." (PMID 34761108, 2021). "NCK1-AS1 via miR-22-3p/IGF1R axis could enhance chemoresistance in glioma." (PMID 34178658, 2021). "Given the establishment of the importance of IGF1R axis in gliomagenesis and TICs maintenance, at least the ones related to OPCs, in the current study, interruption of the communication from the ligand side can be a novel strategy for IGF1R‐based anti‐glioma therapy." (PMID 33173731, 2020). "Additionally, IGF1R plays an important role in tumor cell metastasis and survival of malignant tumor cells, and is essential for the regulation of adaptive radioprotection in glioma stem cells." (PMID 30013477, 2018). "However, the association of miR‐497 and chemosensitivity of IGF1R/IRS1 pathway has not yet been explored in glioma." (PMID 28064447, 2017). "The most down—regulated miRNA (hsa—miR—383) found in the investigated GP group may be involved in the promotion of glioma cell invasion by targeting the insulin-like growth factor 1 receptor gene (IGF1R) via AKT signalling that had been demonstrated previously." (PMID 25950799, 2015). "The insulin-like growth factor 1 receptor (IGF1R) is a transmembrane receptor tyrosine kinase that plays a crucial role in the development and progression of various cancers, including gliomas." (PMID 40290443, 2025). "The relationship between gliomas and IGF-1R has been previously reported inhibition of IGF-1R can effectively suppress the growth of GBM cells either by directly reducing tumor cell proliferation or through indirect antiangiogenic effects." (PMID 38665430, 2024). "INHEG activation enhances rRNA 2’-O-methylation, thereby increasing the expression of oncogenic proteins including EGFR, IGF1R, CDK6 and PDGFRB in glioma cells." (PMID 37980347, 2023).